NEAT1 (nuclear paraspeckle assembly transcript 1)
Diseases named in the same sentence as NEAT1 in open-access papers (continued):
Sharing a sentence is not in itself a finding about the gene and the disease.
glioma (continued). "Previous studies have reported an increase in NEAT1 levels in high-grade glioma specimens compared to control and low-grade glioma." (PMID 39032650, 2024). "Research has shown that NEAT1 is markedly upregulated in gliomas in comparison to surrounding non‐neoplastic tissues." (PMID 39453684, 2024). "We further showed usage of the NEAT1 proximal polyadenylation site (PAS) is a critical mechanism that controls glioma NEAT1 isoform production." (PMID 39032650, 2024). "Further experiments demonstrated the mediative role of miR-125a and its target gene STAT3 in NEAT1-induced polarization of M2-like macrophages that promote glioma progression." (PMID 39061140, 2024). "LncRNA NEAT1 regulates pyroptosis in glioma cells and colorectal cancer cells by targeting miR-296-5p or miR-448; while its high expression promotes ferroptosis in non-small cell lung cancer." (PMID 37313458, 2023). "CYTOR, NEAT1, LOXL1-AS1, and ZNF295-AS1 were significantly associated with glioma grade and survival." (PMID 36597408, 2023). "NEAT1 promotes glioma development by upregulating SOX2 expression through the suppression of miR-132." (PMID 37403043, 2023). "One study has demonstrated that lncRNA KCNQ1OT1, LINC01278, lncRNA MIRLET7BHG and lncRNA NEAT1 can act as upstream targets of miR-296-5p and regulate the occurrence and development of glioma." (PMID 37313458, 2023). "miR-27b/ ITGA5 axis participated in the regulation of tongue squamous cell carcinoma epithelial-mesenchymal transition and lncRNA NEAT1/ miR-128-3p/ITGA5 axis was involved in the regulation of glioma progression." (PMID 36742137, 2023). "In glioma tissues, lncRNA NEAT1 specifically interacts with PGK1 to block the ubiquitination and degradation of PGK1." (PMID 37723547, 2023). "CRNDE showed low expression in WHO grade II samples, while the expression of LINC00665 and NEAT1 remained stable across glioma grades in the CGGA cohorts." (PMID 36090045, 2022). "Nuclear paraspeckle assembly transcript 1 (NEAT1) has been reported to be an important lncRNA participating in progression of a lot of tumors, including glioma." (PMID 35123484, 2022). "NEAT1 overexpression is essential for PGK1 stability in glioma cells, thus promoting glycolysis of glioma cells." (PMID 35123484, 2022). "Targeting NEAT1 regressed glioma cell proliferation, migration, and invasion through sponging miR-132, thereby inhibiting Sox2 expression." (PMID 35531099, 2022). "Collectively, our study found that NEAT1 enhances glioma cell proliferation and glycolysis in vitro and in vivo." (PMID 35123484, 2022). "For example, NEAT1 knockdown suppressed the metastatic ability of glioma by upregulating SRY-Box transcription factor 2 (SOX2) repression by miR-132." (PMID 35030969, 2022). "Expression of many lncRNAs has been shown to be dysregulated in glioma, such as the up-regulation of NEAT1, HOTAIR, FOXM1-AS, H19, SOX2OT, and HCP5 expression and the down-regulation of GAS5, NBAT-1, and CASC2 expression." (PMID 35359381, 2022). "LncRNA NEAT1 is upregulated in glioblastoma patients and glioma stem cells and is involved in resistance to TMZ treatment." (PMID 36499136, 2022). "In vitro experiments, including CCK-8, colony formation, ECAR, and lactate detection assays were performed to evaluate the effect of NEAT1 on proliferation and glycolysis of glioma cell." (PMID 35123484, 2022). "To dissect the potential molecular mechanism of NEAT1 regulating proliferation and glycolysis of glioma cells, we designed a biotin-conjunct probe followed by RNA pulldown assay and protein mass spectrometry analysis." (PMID 35123484, 2022). "Studies revealed that NEAT1 promotes glioma progression via activating several important signaling pathways, including mTOR and Wnt signaling." (PMID 35123484, 2022). "It has been proven that knockdown of NEAT1 upregulates let-7g-5p, inhibiting glioma stem cell (GSC) malignant behavior including proliferation, migration, and invasion and reducing TMZ resistance." (PMID 36499136, 2022).
glioma (continued). "NEAT1 lncRNA is upregulated in glioma to inhibit the expression of miR-132 by removing miR-132′s negative regulation on SOX2, thus promoting gliomagenesis." (PMID 36009578, 2022). "Clinically analysis using CGGA, TCGA datasets and our samples, we revealed that NEAT1 is overexpressed in GBM than low grade glioma and normal brain tissues." (PMID 35123484, 2022). "Lastly, NEAT1 expression was positively correlated with PGK1 in glioma samples, indicating NEAT1 and PGK1 are potential biomarkers for glioma." (PMID 35123484, 2022). "The NEAT1 content in glioblastomas is more than twofold higher than that inless aggressive types of gliomas." (PMID 34707896, 2021). "Taken these together, we found that silencing NEAT1 inhibited the proliferation of glioma cells by regulating the miR-98-5p/BZW1 axis." (PMID 33393590, 2021). "NEAT1 directly targets miR-449b-5p as a molecular sponge and promotes upregulation of c-Met, a direct target of miR-449b-5p, to increase pathogenesis in glioma." (PMID 33980320, 2021). "Most often, NEAT1 exhibits its oncogeniceffect in gliomas by binding to various miRNAs (e.g., miR-107)." (PMID 34707896, 2021). "As expected, NEAT1 expression levels elevated with the ascending of pathological grades of glioma tissues whereas miR-128-3p showed an opposite trend." (PMID 34263426, 2021). "Accumulating evidences indicate that long non-coding RNA nuclear paraspeckle assembly transcript 1 (NEAT1) promotes the progression of glioma." (PMID 34263426, 2021). "We found that NEAT1 levels in 30 human glioma tissues were higher than those in peritumor tissues, which is consistent with the results of previous studies." (PMID 33393590, 2021). "To evaluate the prognostic relevance of PTRF, NEAT1, and PD-L1 expression, we analyzed glioma data from TCGA, CGGA, and Rembrandt databases." (PMID 35069587, 2021). "The present study is conducted to investigate the clinical feature about NEAT1 in glioma and identify the molecular mechanism of NEAT1 in the prognosis of glioma." (PMID 33393590, 2021). "By activating microRNA let‐7e, down-regulation of NEAT1 can repress the advanced progression of glioma stem cells." (PMID 33393590, 2021). "To identify the role of lncRNA NEAT1 in glioma, we performed real-time PCR to measure the expression level of lncRNA NEAT1 in 30 pairs of glioma tissues." (PMID 33393590, 2021). "It has been confirmed that LncRNAs can function as molecular signaling mediators to regulate glioma phenotypes through mediating the expression of genes in NEAT1-WNT/β catenin 27 and CRNDE- mTOR signaling pathway." (PMID 34093827, 2021). "To further affirm the relevancy between NEAT1 and miR-128-3p on glioma growth in vivo, we established a tumor model in nude mice." (PMID 34263426, 2021). "Above all, NEAT1 inhibition impaired the high degree of malignancy of glioma cells triggered by the reduction of miR-128-3p." (PMID 34263426, 2021). "In our present study, we further demonstrated that NEAT1 was up-regulated and acted as ceRNA in gliomas." (PMID 33393590, 2021). "In this section, we summarize and discuss the role of the NEAT1/miRNA/target axis in nervous system tumors, including glioma, retinoblastoma, and neuroblastoma." (PMID 34512157, 2021). "Taken together, our studies provide novel insights into the NEAT1/miR-128-3p/ITGA5 axis in glioma, and are expected to guide future development of therapies for glioma treatment." (PMID 34263426, 2021). "NEAT1 is an lncRNA confirmed to be upregulated in gliomas and promotes cell migration and invasion, in addition to suppressing apoptosis in glioma cells." (PMID 34540695, 2021). "The results showed that NEAT1 was dramatically increased in glioma cell lines (except A172) relative to HA, especially in U87MG and U251MG." (PMID 34263426, 2021). "In glioma, lncRNA NEAT1 is upregulated, which can promotes tumor progression by inhibiting miR-132 to promote SOX2 expression." (PMID 34091587, 2021).
glioma (continued). "Expression of NEAT1 has been found to be elevated in serum samples of glioblastoma patients and glioma stem cells isolated from related cell lines." (PMID 34178658, 2021). "For instance, NEAT1 promoted glioma stem cell formation, which is critical for chemoresistance, via activating the Wnt/β-catenin pathway." (PMID 34322395, 2021). "MALAT1, NEAT1, and H19 are among lncRNAs that affect the response of glioma/glioblastoma to chemotherapy." (PMID 34178658, 2021). "Aberrant overexpression of the long noncoding RNA nuclear-enriched abundant transcript 1 (NEAT1) has been reported in many types of solid tumors, such as lung cancer, esophageal cancer, colorectal cancer, hepatocellular carcinoma and glioma." (PMID 33393590, 2021). "Next, knockdown of NEAT1 significantly increased the expression of miR-98-5p in glioma cells and overexpression of NEAT1 significantly induced the expression of miR-98-5p in glioma cells." (PMID 33393590, 2021). "The luciferase reports, RNA pull-down assay, and RNA immunoprecipitation assay were conducted to determine the relevance of NEAT1 and miR-128-3p in glioma." (PMID 34263426, 2021). "The expression level of NEAT1 significantly increases in glioma tissues and promoted cell migration and invasion by regulating the miR‐139‐5p/CDK6 pathway." (PMID 34540695, 2021). "By binding to anti-oncogene miR-128-3p in the nucleus, NEAT1 enhanced tumorigenesis and glioma development." (PMID 34263426, 2021). "Results of the present work revealed upregulation of NEAT1 and downregulation of miR-128-3p in surgical glioma tissues and GBM cell lines, respectively." (PMID 34263426, 2021). "In order to validate the role of BZW1 in NEAT1/miR-98 axis in glioma, NEAT1-siRNA and BZW1 vector were transfected and the transfection efficiency was measured in the U87." (PMID 33393590, 2021). "In this study, we evaluated that NEAT1 expression levels in glioma tissues were higher than those in peritumor tissues." (PMID 33393590, 2021). "Results of cell viability, motility, apoptosis, and cycle affirmed that NEAT1 was indeed a pro-oncogenic factor whereas miR-128-3p functioned as a tumor suppressor miRNA in glioma cells." (PMID 34263426, 2021). "Relative levels of NEAT1 and miR-128-3p expression in human glioma samples and GBM cells were detected using quantitative real-time PCR." (PMID 34263426, 2021). "Expression of MAP3K1, as a target of let-7g-5p, has been enhanced by NEAT1, Therefore, NEAT1 enhances malignant features of glioma stem cell and chemoresistant phenotype via let-7g-5p/MAP3K1 axis." (PMID 34178658, 2021). "Further investigations are warranted to elucidate the upstream and downstream mechanisms of NEAT1 overexpression in glioma." (PMID 33393590, 2021). "It has been reported that NEAT1 was up-regulated and promoted tumor progression in glioma, indicating NEAT1 acted as an oncogene in GBM progression." (PMID 33057597, 2020). "NEAT1 is critical for glioma cell growth and invasion, thus suggesting novel therapeutic interventions." (PMID 32443824, 2020). "LncRNA NEAT1 knockdown represses migration and invasion of glioma cells through regulating SOX2 targeted by miR-1326." (PMID 32826866, 2020). "Mechanistic study showed that NEAT1 serves as a competitive endogenous lncRNA sponging miR-449b-5p, inducing c-Met expression thus potentially contributing to the development of glioma." (PMID 32443824, 2020). "Such as, UPF1 regulates the progression of glioblastoma cells by improving the stability of linc‐00313,33 SRSF1 stabilized lncRNA NEAT1 to regulate the cell cycle progression in glioma." (PMID 33128346, 2020). "In the present study, we explored the expression and related mechanisms of nuclear enriched abundant transcript 1 (NEAT1) in glioma stem cells (GSCs)." (PMID 33057597, 2020). "NEAT1 acts as a molecular sponge for miR-449b-5p, which leads to upregulation of c-Met, resulting in glioma pathogenesis." (PMID 32219093, 2020).
glioma (continued). "NEAT1 acts as an oncogene in a series of human cancers including gliomas, where it is regulated by the Epidermal Growth Factor Receptor (EGFR) pathways, and contributes to tumor growth and invasion." (PMID 32443824, 2020). "In line with these clinical results, over-expression of NEAT1 conferred malignancies to glioma, and NEAT1 knockdown inhibited glioma cell proliferation, invasion, and migration." (PMID 32443824, 2020). "Studies have shown that NEAT1 can be used as a scaffold to participate in the chromatin remodeling of glioma cells, promote the increase of the trimethylation level of the promoter of downstream genes, and then promote its expression." (PMID 33168814, 2020). "For example, lncRNA NEAT1 drove the development of glioma through inhibiting miR-132 to enhance the expression of SOX2." (PMID 32009853, 2020). "For example, miR-107 is found upregulated in glioma cell lines and binds to LncRNA nuclear paraspeckle assembly transcript 1 (NEAT1)." (PMID 31151434, 2019). "Growing evidence suggests that lncRNA NEAT1 are involved in the regulation of Akt phosphorylation in glioma." (PMID 31438982, 2019). "LncRNA NEAT1 is notably increased in glioma, and promotes the prostate cancer cell growth through the Akt pathway." (PMID 31438982, 2019). "Second, we demonstrate that inhibition of COX-2, mPGES-1 and CYP4A by ISL blocks the angiogenic Akt signaling in glioma through ceRNA effect of miR-194-5p and long non-coding RNA NEAT1." (PMID 31438982, 2019). "Herein, we demonstrated that downregulation of lncRNA NEAT1 by ISL inhibited Akt phosphorylation by targeting miR-194-5p in the U87 glioma cells." (PMID 31438982, 2019). "lncRNA NEAT1 inhibits cell invasion by targeting miR-132 to modulate SOX2 expression in glioma cells." (PMID 31631065, 2019). "NEAT1 silencing inhibits glioma progression, and NEAT1 induces glioma progression by regulating miR-107 as its endogenous sponge." (PMID 31151434, 2019). "With a high expression in tumor tissues and cells, NEAT1 exerted tumorigenesis-promotive function in glioma." (PMID 30053878, 2018). "Although we identified the promotive function of NEAT1 in glioma and investigated its relationship with miR-132 and SOX2, the limitations should be pointed out and made up in the future." (PMID 30053878, 2018). "NEAT1 negatively regulated the expression of miR-132 in glioma while miR-132 targeted SOX2 to down-regulate its expression." (PMID 30053878, 2018). "Higher NEAT1 expression correlated with a larger tumor size, higher WHO grade, recurrence rate, and unfavorable overall survival, supporting NEAT1 as a potential prognostic predictor of glioma patients." (PMID 30116729, 2018). "After knocking down NEAT1 in glioma cells U251 and U87, miR-132 expression tremendously increased, further verifying the regulatory relationships between NEAT1 and miR-132." (PMID 30053878, 2018). "In consequence, NEAT1 knockdown was effective in reducing aggression and proliferation of glioma cells." (PMID 30053878, 2018). "Regulated by EGFR pathway activity, NEAT1 is critical for glioma cell growth and invasion through the WNT/β-catenin pathway." (PMID 29458374, 2018). "The invasive and migratory abilities of glioma cells were weakened by the up-regulation of miR-132, and offset by elevating NEAT1 expression." (PMID 30053878, 2018). "Our results also confirmed the inhibitory effect of NEAT1 knockdown on the viability and invasion of glioma cells." (PMID 30053878, 2018). "An overexpression of lncRNA NEAT1 in glioma tissue positively correlates with glioma grade, and a lower NEAT1 expression correlates with longer survival of glioma patients." (PMID 30583549, 2018). "Meanwhile, the migratory and invasive activities of glioma cells are also obviously suppressed by NEAT1 knockdown." (PMID 30053878, 2018). "Glioma stem cells transfected with NEAT1 shRNA exhibited weaker proliferation, migration and invasion than that of those cells transfected with control shRNA." (PMID 30374364, 2018).
glioma (continued). "As an oncogene, lncRNA NEAT1 played a role in glioma by targeting miR-132 and then indirectly promoting SOX2 expression." (PMID 30053878, 2018). "Glioma cell viability decreased by the transfection miR-132 mimics, and reversed by NEAT1 overexpression." (PMID 30053878, 2018). "The data support a critical role of NEAT1 in the maintenance of stemness of glioma cells via multiple pathways." (PMID 28872613, 2017). "Upon treatment with the DNA damage-inducing agent resveratrol, NEAT1 is up-regulated in the glioma cell lines U251 and U87." (PMID 28293170, 2017). "NEAT1 promotes glioma pathogenesis by regulating glioma cell proliferation, invasion, and migration." (PMID 28293170, 2017). "NEAT1 is an lncRNA confirmed to be upregulated in gliomas, and promotes cell proliferation, migration and invasion while suppressing apoptosis in glioma U87 and U251 cells." (PMID 27556696, 2016). "NEAT1 is upregulated and has important functions in a variety of cancers including glioma, such as favors cell proliferation, migration and invasion and impaired apoptosis." (PMID 27556696, 2016). "Quantitative real-time PCR (qRT-PCR) was conducted to determine the expression of NEAT1 in two additional glioma cell lines and GSCs." (PMID 27556696, 2016). "Additionally, SE-lncRNAs such as TMEM44-AS1, CCAT1, LINC00152, and NEAT1 are identified as facilitators of glioma malignancy, reinforcing the prognostic and therapeutic potential of SE-lncRNA signatures." (PMID 40565099, 2025). "In GBM, lncRNA NEAT1 is highly expressed in recurrent gliomas compared to primary gliomas." (PMID 40141179, 2025). "Moreover, NEAT1 stimulated glioma activity using modulating mTOR signalling, demonstrated in both in vivo and in vitro settings." (PMID 40387409, 2025). "This study provides evidence that exosomes carrying NEAT1 may serve as a potential therapeutic target for glioma therapy." (PMID 39061140, 2024). "Moreover, dysregulation and the oncogenic function of NEAT1 have been extensively studied in various types of cancer including glioma." (PMID 39032650, 2024). "Finally, we demonstrated the forced increase of NEAT1_2 upon NEAT1 PAS deletion is responsible for driving glioma cell migration and promoting the expression of genes implicated in the regulation of cell migration." (PMID 39032650, 2024). "Furthermore, we found that the RBP quaking (QKI), a glioma risk factor, regulates the biogenesis of NEAT1 isoforms through facilitating NEAT1 PAS usage in glioma cells." (PMID 39032650, 2024). "The elevated expression of LncRNA-NEAT1 was found in glioma cells after radiotherapy, chemotherapy, and DNA damage stimulation, and NEAT1 could promote the malignant biological activities of GSCs." (PMID 39061140, 2024). "Previous studies have specifically explored the role of NEAT1 in glioma migration." (PMID 39032650, 2024). "This raises an intriguing possibility that NEAT1 isoforms may impact distinct pathways in the cellular landscape of glioma." (PMID 39032650, 2024). "In glioma, the lncRNA NEAT1 promotes tumour progression by regulating the miR‐98‐5p/BZW1 axis." (PMID 39462268, 2024). "In this regard, the frequent deletion of the QKI locus found in GBMs may affect NEAT1 isoform biogenesis and glioma tumor development." (PMID 39032650, 2024). "To further investigate whether and how deletion of the NEAT1 PAS may alter transcriptome-wide mRNA splicing in glioma, we utilized the iRNA-seq package to analyze how splicing efficiency of the identified DEGs are affected." (PMID 39032650, 2024). "The expression level of NEAT1 in glioma tissues and cells was detected by qRT‐PCR." (PMID 39453684, 2024). "Some other SE-lncRNAs, including CCAT1, LINC00152, and NEAT1, may also facilitate the malignant phenotype of gliomas." (PMID 37004060, 2023). "GBM tissues have higher expression of NEAT1 than low-grade glioma and normal brain tissues." (PMID 37345170, 2023).